RNU6-1110P (RNA, U6 small nuclear 1110, pseudogene)
Gene: Small nuclear RNA gene on chromosome 16 (58,384,442 to 58,384,542, reverse strand). Ensembl gene ENSG00000252271.
Homologues: Orthologues: chimpanzee U6 (99% identical), macaque U6 (87% identical), pig U6 (64% identical), rabbit U6 (59% identical). Paralogues in human: RNU6-1019P (77% identical), RNU6-1075P (76% identical), RNU6-187P (76% identical), RNU6-41P (76% identical), RNU6-44P (76% identical), RNU6-753P (76% identical), RNU6-1124P (75% identical), RNU6-20P (75% identical), RNU6-269P (75% identical), RNU6-29P (75% identical), RNU6-433P (75% identical), RNU6-790P (75% identical), and 1286 more.